SOX2 (SRY-box transcription factor 2)
Diseases named in the same sentence as SOX2 in open-access papers (continued):
Sharing a sentence is not in itself a finding about the gene and the disease.
tumor (continued). "In contrast to SOX2, SOX9 show not cell specificity, as it expression expanded from hair follicles in normal skin to the basal layer in tumours across all models, regardless of cell of origin." (PMID 41507151, 2026). "In SOX2-expressing tissues such as the oral mucosa and salivary glands, deletion of Sox2 in KRT14-Cre–driven models did not impair tumor formation, growth kinetics, or histological identity." (PMID 41266112, 2026). "Whilst conditional Sox2 deletion did not affect tumorigenesis or tumour growth in the K14:BRAFV600E-SOX2fl/fl model, it significantly delayed tumour onset and tumour growth in the Ivl:BRAFV600E-SOX2fl/fl model." (PMID 41507151, 2026). "KLF4, SOX2, and NANOG had low expressions in tumor tissue compared with its adjacent non-malignant (NM) counterpart, while no significant changes were found for c-MYC and OCT4 gene expressions." (PMID 41463190, 2025). "Immunohistochemical staining of tissue samples confirmed high expression levels of PP1γ, YAP1, SOX2, and NANOG proteins in tumor tissues compared to adjacent non-cancerous tissues." (PMID 40626009, 2025). "E2F1 expression was significantly increased by the greatest multiple in the high stemness score group compared to SOX2 and MYC, as well as in the tumor and adjacent normal tissues group, early(I + II) and advanced stage (III + IV) group." (PMID 40886002, 2025). "In urethane-induced lung tumors, nuclear positivity of SOX2, OCT4, and NANOG was observed in some cells in both TC2N+/+ and TC2N-/+ tumor groups (red arrows), while no significant staining signal was observed in the TC2N-/- tumor group." (PMID 39849581, 2025). "In contrast, although SOX2 and SOX10 showed positive immunostaining, they did not exhibit statistically significant correlations with histopathological indicators of tumor aggressiveness." (PMID 41012776, 2025). "Post-treatment analyses showed that compared to non-treated tumor cells, the tumor cells remaining after CAR33-T cell treatment were CD33-negative/low and exhibited elevated levels of CSC markers such as SOX2 and OCT3/4." (PMID 39893165, 2025). "Sox2, on the other hand, is expressed in LNM1, LNM2 cells, and tumor cells, but not in melanocytes or other cell lineages in our dataset." (PMID 40571713, 2025). "Immunohistochemically, the tumor cells were positive for GFAP and S‐100 protein, weakly positive for SOX2, focally positive for synaptophysin, and negative for TTF‐1, neurofilament protein, NeuN, EMA, chromogranin, and BCOR." (PMID 39492623, 2025). "With the exception of HCC1599 xenografts, which expressed N1-ICD but were SOX2 negative, tumors of all other models contained tumor cells expressing both N1-ICD and SOX2." (PMID 39478150, 2024). "These round tumour cells were rich in clear cytoplasm and positive for Oct4, SALL4, PLAP and CD117 and negative for CK, CEA, CD30 and SOX2." (PMID 37118812, 2023). "Prrx1 enhances the acquisition of stemness in non-stem tumor cells and maintains GSC stemness by promoting CD133 and SOX2 expression through activation of TGFβ pathway." (PMID 36635261, 2023). "CTC CNAs, including amplifications of MYC, BCL6, DDR2, SOX2 and deletions of CDKN2A/B, were more likely to be shared with residual rather than primary tumor." (PMID 35087134, 2022). "IF detection demonstrated that the cells in the tumor bulk originated from human cells and displayed a prominent CD105+ expression and no SOX2 immunoreactivity." (PMID 36038950, 2022). "SOX2 staining was specific to GBM cells, as the vast majority of endogenous SOX10+ OPCs were negative for SOX2 in areas of tumour infiltration." (PMID 33846316, 2021).
tumor (continued). "PDGFRα was also highly coexpressed by the ASCL1+ and OLIG2+ (not shown) tumor cells, whereas GFAP and to a lesser extent S100β and NEUN, although found in some parts of the tumor, did not overlap significantly with SOX2 or ASCL1." (PMID 32573857, 2020). "c, Tumor incidence showing the tumorigenesis of the indicated serial of cell numbers of METTL3 knockdown and control SW620 cells with or without SOX2 overexpression." (PMID 31230592, 2019). "While cisplatin and doxorubicin in vitro treatment reduced SOX2 and OCT4 expression in primary tumor cells, methotrexate did not affect SOX2 and OCT4 expression." (PMID 28934267, 2017). "Although CD24 was excluded from the analysis since it was expressed by most tumor cells in our ascitic effusion samples, CD44+CD117+ cells significantly overexpressed NANOG, SOX2 and OCT4, compared with the negative counterpart CD44+CD117−." (PMID 28726781, 2017). "ALDH1 positive cells from 5-8F and CNE-2 cell lines induced tumour growth, contained higher percentage of SP subpopulation and had higher levels of OCT4, BMI1, KLF4 and SOX2 transcripts than ALDH1 negative cells." (PMID 28959019, 2017). "The expression of CD15, SOX2, SOX9, YKL40 and the proliferation marker Ki67 tended to be higher in cells derived from tumor core compared to UA cells, but the difference was not statistically significant." (PMID 27605047, 2016). "During this differentiation, an EC-intermediate step is skipped (no upregulation of SOX2) and a strong upregulation of germ layer differentiation markers, like AFP (also a yolk-sac tumor marker) and HAND1 was observed." (PMID 27283990, 2016). "We observed that the expression of 10 of 12 CSC-related markers (CD90, ALDH1, CK7, CK19, OCT4, SOX2, vimentin, nestin, CD13 and EpCam) was not significantly different between the tumor tissues and peritumoral tissues." (PMID 27329727, 2016). "Given that SOX2 and SOX9 H-scores were not that different between basal and suprabasal layers, for P-S6, we only scored the fraction of tumor cells that stained positive." (PMID 27880766, 2016). "Surprisingly, tumours do not express YFP, indicating that the cell of origin of mouse ACP is not a targeted SOX2+ve cell." (PMID 25611703, 2015). "At this time, molecular profiling of the patient primary tumor was performed and it revealed FGFR1 overexpression, SOX2 amplification and no PDGFRA amplification." (PMID 25126591, 2014). "In our study, statistically similar levels of SOX2 and TERC amplifications occurred in all stages of the disease regardless of lymph node status and tumor classification." (PMID 24410919, 2014). "Further analysis of the primary tumor by RT-PCR revealed the expression of the pluripotency markers POU5F1, NANOG and SOX2 in CD44+ but not CD44− subpopulations." (PMID 21124918, 2010). "However, it is not clear whether or not SOX2 has tumour-suppressive function in gastric cells." (PMID 18268498, 2008). "Notably, most mice reached humane endpoints within 3 wk of tumor detection by BLI, mirroring the rapid progression observed in the KRT14-Cre; NCT models, regardless of the Sox2 status." (PMID 41266112, 2026). "Additionally, SOX2 knockdown did not significantly affect the expression levels of OCT4 and NANOG, but markedly reduced the number of tumor spheres formed." (PMID 40821114, 2025). "However, GSEA of gene expression profiles of Sox2-deficient CPP resulted in a negative normalized enrichment score for Sox2-wild-type CPP, suggesting alterations in these pathways in tumor cells following Sox2 knockout." (PMID 40128799, 2025). "Among the SOX family proteins studied, the SOX3 protein plays a role in the regulation of cell proliferation in oral melanomas, and it is suggested that the SOX2 and SOX10 proteins are constitutively expressed in these neoplasms, without a determining role for aggressiveness." (PMID 41012776, 2025).
tumor (continued). "Interestingly, HCC1599 tumors expressed the highest number of N1-ICD-positive cells (83% of tumor cells positive for N1-ICD), while being completely negative for SOX2 staining." (PMID 39478150, 2024). "Tumor-spheres in Lu99 cells expressed ALDH1A1, Nanog, Oct4, and Sox2 genes, but not CD133." (PMID 36551502, 2022). "If we extend the marker genes to include the non-classical ones such as MUC1 for ADC, SOX2 for SCC, and ASCL1 for NET, the mixed-lineage cancer cells were notably observed in all of the sixteen patients from whom we isolated epithelial cells in tumor tissues." (PMID 35962452, 2022). "Since TM impacted metastasis and not primary tumor growth, using the lentiviral SOX2/OCT4-GFP promoter reporter system, we lineage traced a subpopulation of SOX2+ OCT4+ cancer cells within the primary tumor, that exhibit stem cell phenotypes, and enhanced potential for metastasis in TNBC models." (PMID 34911956, 2021). "To compare the expression of Sox2 in the absence or presence of HBO, we collected tumour tissues from primary GBM and tumour implantation from mouse brains and observed Sox2 was expression in the group without HBO treatment; however, after HBO treatment, Sox2 expression decreased significantly." (PMID 33986256, 2021). "While Krt5 was positive, Sox2, a marker and driver of SCC, was negative in all samples, while positive cells were detected in basal cells of the trachea, suggesting a co-expression rather than squamous differentiation of tumor cells." (PMID 33738287, 2021). "However, the deletion of Apc in both Hesx1-expressing embryonic precursors, or SOX2 + adult stem cells, completely fails to generate ACP-like tumours." (PMID 34019103, 2021). "However, both mTOR complexes inhibition, rather than mTORC1 and PI3K inhibition, depletes SOX2 and OCT4 protein levels in glioblastoma cells and suppresses the ability to form tumor-spheres as well." (PMID 33828530, 2021). "In addition, the results of in vivo experiment suggested that SOX2‐expressing tumours contained lower numbers of CD8+ CTLs and that those infiltrating T cells expressed higher levels of PD‐1 than SOX2‐negative tumours." (PMID 33605033, 2021). "Although the molecular markers that can be used to label tumor stem cell-like phenotypes were not very clear yet, SOX2, OCT4, and NANOG, which are transcription factors, have been confirmed to be the main regulatory factors to maintain tumor stem cell-like phenotypes." (PMID 32766132, 2020). "Here, we compared mRNA expression of NANOG and SOX2 between tumor cells co-cultured with or without CAFs and found decreased mRNA expression of SOX2 in tumor cells co-cultured with CAFs from LK1108, but in the other two cell lines, a tendency to increased expression of SOX2 and NANOG was found." (PMID 33353547, 2020). "In the CAMK2A-EZH2-SOX2 pathway, CAMK2A is the only factor specifically expressed in tumor but not normal lung, and thus might be a relatively safe treatment target compared with non-specifically inhibiting EZH2 and SOX2." (PMID 32483123, 2020). "SORE6+ cells were enriched for SOX2 and exhibited CSC features, including a greater ability to proliferate and form gastrospheres in non-adherent conditions, a larger in vivo tumor initiating capability, and increased resistance to 5-fluorouracil (5-FU) treatment." (PMID 32093282, 2020). "However, Oct4, Nanog and Sox2 mRNA levels were significantly increased in the ALM201-treated xenografts, consistent with the lack of anti-CSC activity in the tumour xenograft setting." (PMID 31772325, 2020). "SOX2 antibodies are specific (>90%) markers for SCLC, but are rarely found in patients with other tumours, whether neurological symptoms are present or not." (PMID 30445363, 2019). "We thus propose that in response to anti-proliferative treatment, the regeneration capacity of a tumor resides in a surviving niche of specialized, non-replicating tumor cells that express the CD133 and OCT4/SOX2 stem cell markers and form tubular-like structures." (PMID 31267022, 2019).
tumor (continued). "Exploring the tumorigenic properties of OCT4, SOX2, and NANOG in HaCaT cell line, which did not form tumor in vivo, we found that it is possible to obtain tumorigenic cells from nontumorigenic cells, suggesting that they have CSC properties mediated by the presence of these transcriptional factors." (PMID 31885625, 2019). "The expression of pluripotency markers, OCT3/4, NANOG, SOX2, and LIN28A, did not exhibit significant correlation with tumor formation latency and incidence, and the integration of reprogramming factor genes into genome of hiPSCs did not also affect the transcript expression." (PMID 30286143, 2018). "In this murine model, CD34− and Sox2− cells were both able to form tumours after transplantation, producing CD34- and Sox2-positive and -negative populations in similar proportions to the parental tumour." (PMID 29991569, 2018). "Interestingly, expression of Nanog and Sox2, as well as SSEA-4, another typical pluripotency marker, was not significantly changed by OCT4A overexpression in tumor cells." (PMID 28186969, 2017). "It is exciting to speculate that the CSC in MDBMSCC undergo EMT and preferentially express OCT4, pSTAT3, SOX2, and NANOG and potentially lose the expression of EMA and CD44, as none of these cells outside of the tumor nests express EMA or CD44." (PMID 27532037, 2016). "Sox2/GFAP double-labeling revealed a consistent pattern of Sox2 immunopositivity both in reactive GFAP-immunopositive astrocytes and in GFAP-negative cells, at the interface of tumor and non-neoplastic brain." (PMID 25713758, 2015). "We found that CD44- and SOX2-positive CSCs were inhibited if we inhibited mTOR signaling, which prevents the proliferation of NPC cells and reduces secondary tumor volume and weight, but OCT4-positive CSCs were not significantly affected either in vitro or in vivo." (PMID 26202311, 2015). "SiRNA knockdown of SOD2 expression significantly reduced mean TrkAIII SH-SY5Y tumour spheroid volume but, unlike GW441756, did not reduce Nanog, Nestin, SOX2 or CD117 expression in tumor spheroids, implicating SOD2 in the promotion of SH-SY5Y tumour spheroid growth and survival but not staminality." (PMID 24736663, 2014). "The upregulation of SOX2, but not of its heterodimer binding partner OCT4, could imply a negative feed-back loop, with a switch-off for stemness preservation of tumor cells." (PMID 25340937, 2014). "Several studies have showed that synovial sarcoma cells express mRNA transcripts of pluripotency factors such as Sox2, Oct3/4, and Nanog and show stem-cell-like gene expression profiles, and that tumor cells lacking the BAF47 tumor suppressor subunit express stem-cell-like signatures." (PMID 24130893, 2013). "However, SOX2 is not expressed in the β-catenin accumulating clusters in human ACP, but rather in sporadic cells within the tumour." (PMID 22349813, 2012). "Furthermore, when TRAF4 was knocked out, OA could no longer inhibit the expression of SOX2, Olig2, and MMP9, nor did it impair tumor sphere formation." (PMID 39716976, 2025). "A2BR knockdown did not affect tumor growth rate or sensitivity to paclitaxel, but attenuated paclitaxel-mediated increases of the percentage of ALDH+ cells, the number of mammosphere-forming cells, and the mRNA expression of pluripotency factors NANOG, SOX2, and KLF4." (PMID 35401817, 2022). "To explain this connection, we hypothesized that tumor cells with a stem cell phenotype are less dependent on MET signaling, but in tumors lacking the stem cell factor network where SOX2 is included, signaling through MET may be more crucial for cancer progression." (PMID 34069138, 2021). "On the other hand, it has been suggested that both OCT4 and SOX2 expression are associated with early tumor stage and better disease-free survival, raising the possibility that both SOX2 and OCT4 might not be the best targets to eradicate tumor relapse and progression." (PMID 35048028, 2021).
tumor (continued). "The SOX2+ cell progeny (as indicated by “yellow fluorescent protein” or YFP+ signal) increased in abundance during tumor development and growth, but co-localization of YFP and PRL was low, indicating that the large majority of the tumor (PRL+) cells did not descend from the SOX2+ (stem) cells." (PMID 29255445, 2017). "Additionally, the tumor cells were positive for OCT3/4 and TFAP2C and negative for SOX2." (PMID 27283990, 2016). "This suggested that the Snail-mediated EMT process might not be involved in SOX2-dependent induction of colorectal CSCs, although we could not exclude the possibility of involvement of other regulators of EMT process or factors related to tumor microenvironment affected by irradiation." (PMID 33445526, 2021). "Therefore, the expression oncogenic β-catenin in either SOX2 + adult stem cells or HESX1 + embryonic progenitors leads first to the formation of clusters, which are similar to those found in human ACP, and then promote tumour formation in a cell non-autonomous manner." (PMID 34019103, 2021). "However, the narrow spreads in the majority of SOX2, SOX9, and P-S6 expression data may have limited the power of our statistical analyses, and histological tumor grade might not have been sensitive enough to detect differences in the extent of squamous differentiation." (PMID 27880766, 2016). "In addition, overexpression of miR-106b could enhance the tumour-initiating cell capacity without or with IR condition, such as the colony sphere formation capacity and the upregulation of stemness-related genes (CD133, Sox2)." (PMID 26238857, 2015).